PRKACA (protein kinase cAMP-activated catalytic subunit alpha)
Diseases named in the same sentence as PRKACA in open-access papers (continued):
Sharing a sentence is not in itself a finding about the gene and the disease.
cancer (continued). "PHC3-PRKACA was classified as ‘cautionary’ PP-SV, as PHC3 showed potential cancer suppressor effect in PCa, while PRKACA appears to portray oncogenic behaviour." (PMID 38947031, 2024). "Here, we define the tissue distribution of genetic alterations in PRKACA and PRKAR1A that result in PKA activation in cancer and map the multiple conserved pathways downstream of oncogenic PKA signaling, many of which impinge on the expression of c-MYC." (PMID 36692000, 2023). "Protein kinase CAMP-activated catalytic subunit alpha (PRKACA), elastase neutrophil expressed (ELANE), NLRP1, pejvakin (PJVK), and CASP9 were significantly downregulated in 25, 24, 22, 25, and 23 types of cancers, respectively." (PMID 35246158, 2022). "Among these signatures (TNF, TIRAP, CASP9, PLCG1, PRKACA, CASP3, CASP8, CASP4), TNF (Tumor necrosis factor) is currently considered a two-edged sword in cancer development." (PMID 35741587, 2022). "Considering age, several genes responsible for inflammatory protein secretion/activation (KLK3, EDN3), cell-adhesion (PI4KA, AHSAI1) and cancer-related proteins (KLK3, FGFR1/2, PRKACA, and RAC2) were also modulated in AYA-RMS." (PMID 31533233, 2019). "MYC, CDK6, PRKACA, and ERBB2 genes were found to frequently interact with other cancer-related genes." (PMID 29716549, 2018). "Specifically, MYC, CDK6, PRKACA, and ERBB2, all well-known oncogenes and cancer markers, were overexpressed in conjunction with LYL1 gene amplification." (PMID 29716549, 2018). "Correlations between LYL1 amplification and increased expression levels of cancer-related genes (MYC, CDK6, PRKACA, and ERBB2) are also observed." (PMID 29716549, 2018). "There were a larger number of kinases specifically dysregulated in cancer (e.g. PRKACA, CSNK2A1 and MAPK1) compared with other noncancer conditions." (PMID 36688815, 2023). "The discovery of new members of oncogenic pathways, such as that of TTK and potentially PRKACA in the PI3K/AKT/mTOR pathway in this study, may help the identification of alternative targets for cancer treatment." (PMID 37352361, 2023). "The results show that expression of ELANE, PRKACA, CASP3, CASP9 and CASP6 was related to the efficacy of various anticancer drugs, indicating that pyroptosis genes may participate in pan‐cancer signalling pathways and affect the efficacy of anticancer drugs." (PMID 34816605, 2022). "In addition, the five genes (JUN, PRKACA, SMAD2, ESR1, and BCL3) shared by the OV and multi-NCA biomarkers form a small network module and are recognized as cancer-related genes." (PMID 26202601, 2015). "Here, we have used a network-based exploration approach to identify a multi-cancer gene expression biomarker highly connected by ESR1, PRKACA, LRP1, JUN and SMAD2 that can be predictive of clinical outcome in 12 types of cancer from The Cancer Genome Atlas (TCGA) repository." (PMID 26202601, 2015). "Recently, the presence of the PRKACA and PRKACB fusion genes has been detected in various cancers such as bile duct cancers, fibrolamellar hepatocellular carcinoma, and pancreatic cancers, and there is a possibility that this might be implicated in the pathogenesis of cancer 9-11." (PMID 32626531, 2020). "Regarding the molecular basis of FL-HCC, a fusion of the DnaJ heat shock protein family (Hsp40) member B1 gene (DNAJB1) with the protein kinase cAMP-activated catalytic subunit alpha gene (PRKACA) has often been found in such tumors, but its cancer driving property had not been proven yet." (PMID 34912798, 2021).
infection (6 papers, 2014 to 2023). The state of being infected such as from the introduction of a foreign agent such as serum, vaccine, antigenic substance or organism. "The catalytic subunit alpha of PKA (PRKACA) is one of four mitochondrion-related proteins that are less abundant with infection in an LLO-dependent manner, suggesting that PKA-mediated NCLX activation is impaired during L. monocytogenes infection." (PMID 32019800, 2020). "On the contrary, acting as the negative regulators, PRKAA2 and PRKACA, encoding the subunit of AMP-activated protein kinase (AMPK), which have been proven to inhibit glycolysis via AMPK-mTOR-HIF-1α pathway, were downregulated post infection." (PMID 37256871, 2023). "We discovered that 48 h post-infection, the expression levels of GNAS, PRKACA, RAP1A, and VAMP8 were all dramatically downregulated, which inhibited Rap1 activation and transactivation." (PMID 37211158, 2023). "Moreover, kinases found to be upregulated by the infection of HIBCPP cells with both N. meningitidis strains in this analysis (downregulated in control cells) include MAPKAPK2, RPS6KB1, RET as well as AKT1 and AKT2, whereas PRKACA activity was upregulated only by MC58siaD." (PMID 37065199, 2023).
skeletal dysplasia (1 paper, 2026). Any Mendelian diseases that affects growth and development of the skeleton. "Collectively, this supports that the PRKACA variant is pathogenic, and we propose that it is causal for our patient's unique skeletal dysplasia and vasculopathy phenotypes." (PMID 42157491, 2026).
PRKACA also shares sentences with these, for which no sentence is quoted: hypercortisolism (5 papers); Obesity (4); type 2 diabetes mellitus (4); colon cancer (3); Insulin resistance (3); viral infection (3); diabetes (2); liver cancer (2); non-small cell lung carcinoma (2); rectal cancer (2); acrodysostosis (1); acute myocardial infarction (1); adenocarcinoma (1); Adrenal Cushing’s syndrome (1); alcoholism (1); Alzheimer disease (1); astrocytoma (1); cardiovascular diseases (1); chordoma (1); chronic hepatitis (1); chronic myelogenous leukemia (1); colitis (1); colon adenocarcinoma (1); Familial adenomatous polyposis (1); follicular thyroid cancer (1); glioblastoma (1); gynecological cancers (1); heart diseases (1); Hepatic steatosis (1); hereditary leiomyomatosis (1).
A further 30 diseases each share a sentence with PRKACA in 1 paper.